FAM180B (family with sequence similarity 180 member B)
Synonyms: LOC399888
Tractability: Antibody: UniProt places it where antibodies can reach, with high confidence; UniProt predicts a signal peptide or a membrane-spanning region; its Gene Ontology location is reachable by antibodies, with medium confidence.
Gene: Protein-coding gene on chromosome 11 (47,586,207 to 47,589,195, forward strand). Ensembl gene ENSG00000196666.
Subcellular location: Secreted
Gene Ontology:
Molecular function: protein binding
Cellular component: extracellular region
Genetic constraint (gnomAD): Loss-of-function variants: 19 observed, 17.1 expected, observed/expected ratio (o/e) 1.11, 90% interval 0.77 to 1.62. The upper end of that interval is the gene's LOEUF score, 1.62, which puts it in group 6 of 6, group 1 being the genes least tolerant of losing a copy. Missense variants: 212 observed, 228.26 expected, observed/expected ratio (o/e) 0.93, 90% interval 0.83 to 1.04. Synonymous variants: 109 observed, 96.78 expected, observed/expected ratio (o/e) 1.13, 90% interval 0.96 to 1.32.
Homologues: Orthologues: chimpanzee FAM180B (98% identical), macaque FAM180B (96% identical), dog FAM180B (86% identical), rabbit FAM180B (85% identical), pig FAM180B (83% identical), zebrafish FAM180A (18% identical). Paralogues in human: FAM180A (21% identical).
Diseases named in the same sentence as FAM180B in open-access papers:
FAM180B is named in the same sentence as 3 diseases in open-access papers, as found by Europe PMC text mining. Sharing a sentence is not in itself a finding about the gene and the disease. The quoted sentences say what the papers report.
glaucoma (3 papers, 2022 to 2025). Increased pressure in the eyeball due to obstruction of the outflow of aqueous humor. "Interestingly, rs77465292 (near FAM180B) was linked with central corneal thickness, corneal resistance factor, and primary open-angle glaucoma (POAG), but the POAG risk allele was protective for DED." (PMID 40166553, 2025).
FAM180B also shares sentences with these, for which no sentence is quoted: leprosy (1 paper); open-angle glaucoma (1).